MMP1 (matrix metallopeptidase 1)
Diseases named in the same sentence as MMP1 in open-access papers (continued):
Sharing a sentence is not in itself a finding about the gene and the disease.
tumor (continued). "Under normoxia, MMP1 and integrin (ITGA4) were elevated in TNF-α and TNFα/IL-1β clones; these can degrade the ECM component and play a role in the development of tumour metastasis." (PMID 26759080, 2016). "COL11A1, COL10A1, MMP1 and MMP13 are highly expressed in aggressive molecular subtypes (basal and HER2 tumors) in the Lebanese as their expression increases tumor migration and proliferation." (PMID 27857161, 2016). "Our in vitro data further reveals that GC cell lines over-expression Aplein and its receptor APJ, together with the other cytokines which are known to facilitate tumor metastasis and progression, including IL-1, IL6, MMP1, MMP9 and BMP-2." (PMID 27733135, 2016). "Inflammatory cells surrounding BCC are typically positive for MMP-13, MMP-1, and MMP-9, indicating an essential role of inflammation in modulating tumor progression." (PMID 27271600, 2016). "Our data also demonstrates significant up-regulation of COL11A1, COL10A1, MMP1 and MMP13, and significant down-regulation of COL6A6 and DLK1 in tumor relative to non-tumor adjacent breast tissue." (PMID 27857161, 2016). "Both MMP-1 and MMP-13 are able to cleave native fibrillar collagen, an important step in tumor invasion and metastasis." (PMID 27271600, 2016). "MMP1 has been identified to proteolytically activate G protein coupled receptor (PAR1) and facilitate tumour invasion." (PMID 27324842, 2016). "This indicates a role for MMP-1 in the regulation of cytokine and protease network, particularly related to SCC tumor progression." (PMID 27271600, 2016). "We found that MMP1- a JNK regulated gene and marker for tumor invasion was induced in all genetic combinations under study." (PMID 27327956, 2016). "Silencing TRB3 not only decreased the basal level of critical tumour-promoting factors such as EGFR, COX2, MMP1, MMP-2, MT-MMP, Snail, Twist and c-Myc but also protected them from the IGF-1 induction." (PMID 26268733, 2015). "Although both Fos and Ftz-F1 synergistically contribute to rasV12scrib1 tumor invasiveness, only Fos is required for JNK-induced differentiation defects and Matrix metalloprotease (MMP1) upregulation." (PMID 26398940, 2015). "Mild activation of aPKC drove polarity alterations and a limited degree of neoplasia, along with mild JNK signaling that can activate Mmp1; at these levels, both kinases together were incapable of activating upd3.3." (PMID 25719210, 2015). "In some cases, human pro-MMP1, 2, and 9 can be activated by MMP-7, which further facilitate the metastasis of tumor cells." (PMID 25823818, 2015). "The enhanced MMP1, 2 and 3 expression observed after stimulation with CSC-EVs suggested the capacity of MSCs to modulate matrix remodeling within tumor microenvironment." (PMID 25797265, 2015). "It is well known that MMP1 and MMP13 are strongly related to tumor invasion and metastatic abilities." (PMID 26305549, 2015). "Among these differentially expressed genes, MMP1, MMP12, MMP13 and MMP28 were consistently reduced in hnRNP K-knockdown cells but elevated in tumor cells." (PMID 24885469, 2014). "In tumor cells, EMMPRIN promotes the production of MMP-1, MMP-2, and MMP-9 and facilitates the synthesis of MT1-MMP and MT2-MMP." (PMID 24705283, 2014). "We also evaluated Pit-1 overexpression with MMP-1 and MMP-13 knockdown in a severe combined immunodeficiency (SCID) mouse tumor xenograft model." (PMID 25527274, 2014). "Overexpression of MMP-1 promoted PCa cell invasion and experimental metastasis, and inhibition of MMP-1 activity decreased PCa tumor growth in mice, indicating the importance of MMP-1 in regulating PCa invasion and metastasis." (PMID 25566502, 2014). "High expression of tumor-derived PDGF-BB and MMP-1 correlates with prolonged survival in univariate and multivariate analysis." (PMID 25483099, 2014).
tumor (continued). "Although plasmin has been shown to principally activate MMP-1, -3, and -9, increasing evidence proves that uPA/plasmin can activate pro-MMP-2 and thereby promoting tumor invasion and metastasis." (PMID 25170871, 2014). "Secondly we examined the biological consequence of reduced let-7 expression in NETs and metastasis by western blot analyses and immunohistochemistry on paired FFPE tumor and metastases tissues for HMGA2, BACH1 and MMP1." (PMID 25546138, 2014). "EMMPRIN proteins have been well documented to stimulate the synthesis of MMPs such as MMP-1, MMP-2, MMP-3, and MMP-9 in fibroblast and tumor cells." (PMID 24705283, 2014). "Our data indicated that knockdown of MMP-1 and MMP-13 reduced tumor growth in Pit-1-overexpressing mice." (PMID 25527274, 2014). "Tumor-derived PDGF-BB and MMP-1 are significant and independent prognostic markers for poor survival." (PMID 25483099, 2014). "Since MMP1, MMP3 and MMP9 were involved in tumor invasion and metastasis and can be regulated by NF-κB pathway, we further investigated the effect of RANKL on the MMPs." (PMID 25268581, 2014). "Our data suggest link between MMP1 and CTCs with EMT phenotype and support role of MMPs and EMT in tumor dissemination." (PMID 24972610, 2014). "Although plasmin has been shown to principally activate MMP-1, -3 and -9, increasing evidence proves that uPA/plasmin can activate pro-MMP-2 and thereby promoting tumour invasion and metastasis 53,54." (PMID 25215932, 2014). "On the other hand, the mRNA levels of MMP1 and MMP12 were significantly elevated (14.2- and 56.3-fold, respectively; P < 0.05) in nine matched-pairs of NPC tumor and adjacent normal tissues." (PMID 24885469, 2014). "In CE81T tumor-bearing mice, 1BB1 reduced tumor growth and downregulated TGF-β, cyclin B1, MMP-1, and CXCR4 expression in tumors." (PMID 24130695, 2013). "Though NO has been shown to induce apoptosis it can transcriptionally enhance MMP-1 via the ERK and p38 MAPK pathways resulting in tumor progression and also can result in the overproduction of VEGF." (PMID 23509693, 2013). "Earlier studies have also shown elevation of MMP-1 mRNA in high-grade tumours when compared to low-grade tumours, but also opposite results on MMP-1 immunohistochemical expression and tumour grade exist." (PMID 21835023, 2011). "Relative mRNA expression levels were significantly higher in tumor than in healthy samples for FN1, MMP1, PLAU and SPARC (Wilcoxon test for paired data, p ≤ 0.002)." (PMID 19835631, 2009). "In this study, we assessed the capacity of MMP1, one of the most relevant markers, to detect HNSCC tumor cells in saliva cells; this provided information on its utility as a non invasive diagnostic marker." (PMID 19835631, 2009). "These leukocytes produce cytokines, and growth and angiogenic factors, as well as matrix-degrading proteases (such as the matrix metalloproteinases MMP1, MMP3 and MMP9) and their inhibitors, which allow tumour cells to proliferate, invade and metastasise." (PMID 19050705, 2008). "Interestingly, the presence of MMP-1 within tumour stroma was associated with increased overall survival (log rank test, P=0.044), however no significant survival advantage was observed when MMP-1 protein was assessed in the tumour (log rank test, P=0.331)." (PMID 17311017, 2007). "In the MCF-7 xenograft, low expression of MT1-MMP, MMP-1 and MMP-3 was observed in the tumour cells (1+) as indicated by the faint purple precipitation." (PMID 16430785, 2006). "We analysed and compared the localised expression of MT1-MMP, MMP-1, MMP-3 and β-actin, in both the tumour parenchyma and the surrounding stroma." (PMID 16430785, 2006). "In the mesenteric metastasis, the MDA-MB-231 tumour cells showed a moderate expression of both MT1-MMP and MMP-1 (2+), and low expression of MMP-3 (1+)." (PMID 16430785, 2006). "The Hs578T xenograft showed low expression of MT1-MMP (1+), MMP-1 (1+) and MMP-3 (1+) in the tumour cells." (PMID 16430785, 2006).
tumor (continued). "In the MDA-MB-435 cell line xenograft, we observed moderate expression of MT1-MMP and MMP-1 (2+), and high levels of MMP-3 (3+) in the tumour cells." (PMID 16430785, 2006). "Using quantitative RT–PCR, overexpression of MMP1, MMP3, MMP7, MMP11, MMP12 and MMP13 in desmoid tumours was demonstrated." (PMID 15054469, 2004). "Our results indicated that the expression of MMP-1, -2 and -3 showed different localization patterns, suggesting a unique role of each MMP in tumour progression." (PMID 10362121, 1999). "Notably, sarmentosamide decreased UVB-induced matrix metalloproteinase-1 (MMP-1) expression and tumor TNF-α levels in normal human dermal fibroblasts (NHDFs)." (PMID 40208553, 2025). "To characterize the expression level of MMP1 in tumor tissues compared to adjacent nontumor tissues, we utilized the public TIMER database to analyze MMP1 expression across various cancer types." (PMID 40287412, 2025). "Additionally, ROSs act as second messengers, activating NF-κB, AP-1, and matrix metalloproteinase-1 (MMP1), upregulating IL-8, VEGF, and iNOS, thereby promoting inflammation, proliferation, survival, angiogenesis, and tumor invasion/metastasis." (PMID 40564191, 2025). "In addition, higher expression of MMP1 and MMP12 in patients with tumors post-treatment compared to tumor-free individuals underscores the importance of these markers in predicting treatment response and tumor invasiveness." (PMID 40362553, 2025). "Similarly, matrix metalloproteinases MMP1, MMP3 and MMP12 are crucial regulators of tumour angiogenesis, vascular structure, permeability and integrity." (PMID 39161078, 2025). "RT-qPCR confirmed that MMP1, TFRC, and CXCL8 were upregulated in tumor tissues." (PMID 40809844, 2025). "Our finding indicated that quercetin could regulate the expression of MMP1, which was activated by MAPK signal pathway, as well as other hub CR genes to achieved tumor clearance." (PMID 40535817, 2025). "Therefore, we proposed a bidirectional regulatory loop in the microenvironment, where MMP1 not only responded to NF-κB and EMT pathways but also fed back into these pathways, amplifying tumor-promoting effects." (PMID 40394037, 2025). "MMP1 is an enzyme that degrades ECM components, including collagen, playing a vital role in promoting cancer cell invasion, metastasis, and angiogenesis within the tumor microenvironment." (PMID 40872572, 2025). "EA decreases the expression of MMP1 in RCC tumors, thereby inhibiting tumor invasion." (PMID 40386045, 2025). "Supporting this, KEGG pathway analysis of GFP+RasV12//M6−/− tumor cells also revealed significant enrichment of MAPK (mitogen-activated protein kinase) signaling components, while functional validation confirmed JNK activation through Mmp1 upregulation." (PMID 40846901, 2025). "Notably, MMP1 activated macrophages via the ANXA1-FPR3 pathway, triggering TNFα secretion, which further enhanced NF-κB activation and tumor progression." (PMID 40394037, 2025). "Furthermore, IL-8 (CXCL8) can further upregulate MMP1 expression by activating the STAT3 signaling pathway, thereby enhancing tumor cell invasiveness." (PMID 40809844, 2025). "In addition, shared hub genes across EAC and ESCC—such as COL1A1, SPARC, and MMP1—were enriched in ECM organization and cell adhesion processes, highlighting convergent tumor–stroma interactions." (PMID 40872572, 2025). "MMP1, MMP3, and MMP9 have also been shown to play critical roles in tumor metastasis." (PMID 40486048, 2025). "Similarly, MMP-1 and MMP-3 are engaged in promoting EMT, a process that facilitates tumorigenesis and accelerates the invasion of tumor cells." (PMID 40564842, 2025). "Additionally, a bioinformatic study mirrored our results by demonstrating MMP1, MMP3, and MMP12 up-regulation in CRC, highlighting the potential universal relevance of these MMPs in tumor progression." (PMID 39596132, 2024).
tumor (continued). "In addition, the acidic tumor microenvironment can activate the YAP/MMP1 axis, promote the transition of cell metabolism to PPP, and promote tumor progression." (PMID 39090116, 2024). "Additionally, the unmatched CAFs significantly upregulated the mRNA expression of MMP1, MMP9 and FMOD in tumor cells compared to tumor-matched CAFs." (PMID 38822309, 2024). "Additionally, we also observed increased Mmp1 expression and JNK phosphorylation both in tumor clones and invasive tumor cells in a cell-autonomous manner." (PMID 39516282, 2024). "The upregulation of MMP-1, mediated by AGBL4, may not only promote tumor invasiveness through structural modifications but could also exacerbate inflammation, thereby creating a more conducive environment for tumor growth and spread." (PMID 39007144, 2024). "Increased expression of TIMP1, MMP1, AGRN, UNC5A, and ADAMTS4 was observed, while the expression of UNC5C, TINAG, SPOCK3, and ITGA7 was reduced in the normal FHC cells compared to the HCT8 tumor cells." (PMID 39011483, 2024). "MMP14 and MMP1, members of the MMP family, can directly cleave almost all extracellular matrix components and participate in the degradation of BM and extracellular matrices, thus promoting tumor invasion and metastasis." (PMID 39085893, 2024). "Thus, we also analyzed the mRNA expression of MMP1, MMP9 and FMOD in MACS-separated tumor cells that has been cocultured with tumor-matched and unmatched CAFs or NOFs for seven days." (PMID 38822309, 2024). "The impacts of MMP1 derived from fibroblasts in tumor microenvironment, however, is not well defined." (PMID 38320998, 2024). "In tumor tissue, the MMP1 signal was not restricted to said cell types, but also exhibited by other cells that likely corresponded to tumor cells." (PMID 38891088, 2024). "In the present study, we found MMP1 highly expressed in fibroblasts compared with HNSCC cell lines; and MMP1 from cancer cells had little effect to promote the tumor progression except for the migration ability, whereas MMP1 from fibroblasts enhanced the invasiveness of cancer cells." (PMID 38320998, 2024). "We have previously shown that EGFR and MMP1 act as key players in PM motility and EMT (epithelial to mesenchymal transition)‐like changes, and EPHA5 and PARK2 have been described to both drive and inhibit tumor cell migration." (PMID 36550787, 2024). "Interestingly, the elevated expression of MMP1, MMP2, and MMP3 observed in 3D CAF monocultures was downregulated in 3D co-cultures, indicating a tumor-mediated suppressive effect on these genes." (PMID 39700125, 2024). "Consequently, MMP-1 and MMP-13 synthesis and laminin-332 accumulation are inhibited leading to attenuated cell invasion and tumor growth." (PMID 37864034, 2023). "The increased expression of MMP3 may also activate other MMPs, such as MMP1 and MMP9, which can promote tumor cell passage through the basement membrane and lead to invasion and metastasis." (PMID 36412203, 2023). "In addition, CAFs can remodel the ECM by degrading normal ECM components; secreting multiple matrix proteins; producing MMPs, including MMP-1 and MMP-3; increasing ECM stiffness; and facilitating tumor progression." (PMID 37726803, 2023). "The upregulation of specific MMPs, like MMP-1, -2, -3, and -7, in intestinal inflammation and IBD implicates not only their contribution to the development of CAC but also their potential as biomarkers to identify increasing dysplasia and incipient neoplasia." (PMID 38288108, 2023). "ATF3 is also known as an activator of the tumor invasive potential by up-regulating the expression of the matrix metalloproteinase (MMP) family members (i.e., MMP-1, MMP2, MMP-9 and MMP-13), whose mRNA and protein abundance are correlated with BC invasion and metastasis." (PMID 37447165, 2023).
tumor (continued). "MMP-1 secreted by breast cancer cells promotes angiogenesis and bone metastasis, while MMP-9 released by tumor-infiltrating neutrophils and macrophages triggers the angiogenic switch by releasing VEGF from tumor matrix to sustain angiogenesis-driven intravasation and metastasis." (PMID 37350937, 2023). "CXCL10, CXCL5, MMP1, CXCL12, CXCL11, CXCL2, STAT1, IL‐6 and TLR2 were hub genes in network and may promote or inhibit the homing or of immune cells in tumours and immune cell differentiation, bring intratumoral immune heterogeneity." (PMID 36524848, 2023). "CXCL10, CXCL5, MMP1, CXCL12, CXCL11, CXCL2, STAT1, IL‐6 and TLR2 were hub genes, which may drive the homing of immune cells in tumours and promote immune cell differentiation." (PMID 36524848, 2023). "Interestingly, after PD-L1/CTLA-4 treatment, CTSO, MMP1, SPP1, and TPX2 were significantly up-regulated in tumor cells." (PMID 36225568, 2022). "Together, these data support our hypothesis that vemurafenib-dependent induction of MMP1 and MMP3 is in charge of the rapid tumor cell invasion seen in SEs with the HrasA5 cells." (PMID 35174094, 2022). "Furthermore, integrin α6β1-dependent platelet-tumor cell interaction promotes the release of platelet granules and increases the expression of MMP-1 and MMP-2 in CTCs, favoring the extravasation of tumor cells." (PMID 35936717, 2022). "It is known that MMP1, MMP9, and Twist participate in tumor invasion, metastasis, and VM formation." (PMID 35321317, 2022). "Elevated expression of MMP-1 and TIMP-1 in tumor tissue can predict invasiveness for PTC." (PMID 36551933, 2022). "Previously, MMP-1 and MMP-13 have been shown to be specifically expressed by tumor cells in cSCC." (PMID 36010973, 2022). "FN1, APOA1, CXCL8, MMP1, MMP3, and THBS1 were significantly upregulated in the tumor samples." (PMID 35719376, 2022). "The results showed that tumor cells from nonmetastatic tumors expressed high levels of MMP1, KRT1, and MMP13 and low levels of MGST1, FAM133A, and FMO3." (PMID 36569924, 2022). "However, it is worth noting that since MMP1 levels are significantly higher in ATC than in PDTC, there is a possibility that the difference in survival is more related to tumor type than MMP1 expression, which should be explored by further studies." (PMID 36479070, 2022). "A negative correlation was found in THYM, and other tumor types were positively related to MMP1 expression." (PMID 36727076, 2022). "Given that the JNK pathway has been recognized as an important mechanism controlling cell migration through its target Mmp1 in Drosophila, we first examined whether the JNK pathway is required for Usp8 to promote tumor cell migration." (PMID 35361778, 2022). "Some of its extracellular clients are the matrix metalloproteinase 1 (MMP1), MMP2, MMP3 and MMP9, responsible for promoting tumor cell invasion and metastasis formation through degrading ECM proteins, such as the various types of collagen, fibronectin and laminin." (PMID 36010556, 2022). "The positive correlation between MMP1 and MDSC could be probably explained by MDSC suppression of ability of immune cells to respond thus leading to tumor progression." (PMID 35948625, 2022). "The high-level expression of MMP1 in both CHLA-02 and G401 may indicate a tumor microenvironment conducive to angiogenesis." (PMID 35954348, 2022). "Furthermore, we also confirmed the regulatory effects of cNFIB on CCND1, MMP1, VEGFA, and FOS expression, the key downstream targets of ERK signaling responsible for tumor proliferation and metastasis." (PMID 35039066, 2022). "As for tumor types without normal tissue data in TCGA, we analyzed MMP1 expression by combining TCGA and GTEx data." (PMID 36727076, 2022).